ENSG00000200206
Synonyms: LOC124900360
Gene: Small nucleolar RNA gene on chromosome 15 (86,173,198 to 86,173,270, reverse strand). Ensembl gene ENSG00000200206.
Gene Ontology:
Biological process: RNA processing
Cellular component: nucleolus
Homologues: Orthologues: zebrafish snord74 (73% identical), mouse Gm26224 (70% identical), rat LOC120096384 (67% identical). Paralogues in human: SNORD74B (79% identical).